IL2 (interleukin 2)
Diseases named in the same sentence as IL2 in open-access papers (continued):
Sharing a sentence is not in itself a finding about the gene and the disease.
tumor (continued). "Neutrophils secrete factors that stimulate tumor progression, such as interleukin-2 (IL-2), interleukin-6 (IL-6), interleukin-10 (IL-10), tumor necrosis factor α (TNF-α), and vascular endothelium growth factor (VEGF)." (PMID 34830745, 2021). "In regard to the T-cell response, which has a cardinal role in orchestrating anti-tumor immunity, glucocorticoids deplete T-cells by directly inducing apoptosis, downregulating IL-2 production, and inhibiting their release from lymphoid organs." (PMID 33918733, 2021). "Similar to NK cells, iNKT cells are more difficult to culture, transform and expand that T cells and repeated cell administration or adjuvant use of IL-2 would be necessary to achieve persistence and anti-tumor efficacy." (PMID 33746981, 2021). "Tumour reduction (day 21) and elimination (day 28) when combined with rhIL-12. ↑ Serum IL-2, IFN-γ and TNF-α." (PMID 34769211, 2021). "The T-cell potentiating virotherapy used here consisted of adenoviruses engineered to express tumor necrosis factor alpha and interleukin-2 in the tumor microenvironment." (PMID 34367166, 2021). "Interleukin 2 (IL2) and interferons (IFNs) were the first cytokines used for cancer treatment due to their anti-tumor effects, including inhibition of tumor cell growth and differentiation." (PMID 33579033, 2021). "IFN-γ, TNF-α and IL-2 expression were relatively decreased in tumor-derived TRM cells compared with circulating T cells in melanoma patients." (PMID 34571883, 2021). "The cytokine IL2 is important for growth of T cells and natural killer cells, despite its regulatory effect in cell cycle progression and tumor cell growth." (PMID 33690729, 2021). "Targeting IL-2 to Tnc A1 in combination with temozolomide exhibited an increase in the arrest of tumor progression in subcutaneous and intracranial glioblastoma models compared to monotherapy." (PMID 33803078, 2021). "The expression of the EWSR1-WT1, a fusion protein containing sections of EWSR1 and WT1 transcription factor, in proliferative small round cell tumors can induce the expression of IL-2 and IL-15, which are related to the proliferation of these tumor cells." (PMID 34124041, 2021). "The tumor and organ indexes, including liver and spleen, and IL-2 and IL-10 serum levels also notably decreased, and the amounts of WBC, HGB, and PLT dramatically increased." (PMID 34475822, 2021). "Interleukin 2 enhanced the cytotoxic potential of lymphocytes in two different syngeneic tumor models, thus prolonging subject survival, when lymphocytes were cultured with or injected simultaneously with IL-2." (PMID 33803078, 2021). "Among these, the use of IL-2/anti-IL-2R antibody complexes showed promising results in mouse tumor models." (PMID 33671252, 2021). "First, IL-2 does not specifically activate cytotoxic lymphocytes (CTLs) in the tumor and is used up by many peripheral IL-2 sinks, such as Tregs and non-tumor-specific effector immune cells." (PMID 33986267, 2021). "A hierarchical assembly method combines tumor lysis with a controlled expression of the immune effectors GM-CSF and interleukin (IL)-2, as well as single-chain variable fragments against the checkpoint inhibitors PD-1 or PD-L1." (PMID 34025657, 2021). "The most commonly used approach is intracellular cytokine staining (ICS) focusing on the detection of molecules such as interferon-gamma (IFNγ), tumor necrosis factor (TNF), and interleukin 2 (IL-2), after recognition of tumor-antigens." (PMID 34707600, 2021). "In TIL therapy, TIL is isolated from the tumor site by biopsy or surgery, stimulated and expanded to a large number in vitro with interleukin-2 (IL-2), and then infused back into the patient." (PMID 34112147, 2021). "Surgically resected tumor cells are shipped to the central manufacturing facility where they are fragmented and cultured in the presence of IL-2 to allow TIL to egress from the tumor and expand to approximately 109–1011 cells per culture." (PMID 34140957, 2021).
tumor (continued). "TILs are obtained from surgical tumor specimens and then cultured in vitro with sequential treatment with IL-2 for expansion and anti-CD3 antibody for activation." (PMID 33854960, 2021). "These Tregs suppressed proliferation and cytokine secretion (IFN-γ and IL-2) of anti-tumor effector T cells both at the induction and effector stages." (PMID 33996630, 2021). "IL-2 treatment combined with anti-CD3 therapy was found to restrict tumor cell proliferation and enhance secretion of TNF-α." (PMID 33669271, 2021). "In murine tumor models, Alb-IL2 had superior tumor control and decreased liver metastasis, leading to improved overall survival." (PMID 34790830, 2021). "The injection of exogenous cytokines such as IL-2 and IL-12 has also been successful at promoting anti-tumor immunity." (PMID 33708224, 2021). "Collectively, the vaccine stimulated both of the humoral immunity and cellular immunity through inducing HPV16-L1 expression in the murine tumor tissues and increasing the levels of IL-2 and IFN-γ in serum and genital secretions." (PMID 34635698, 2021). "In a coculture experiment, EGCG was shown to reduce the mRNA expression of PD-L1 in F10-OVA cells and partially restore the mRNA expression of IL-2 in tumor specific T cells." (PMID 34639167, 2021). "Increase the activity of endogenous NK cells with cytokines, especially IL-2, is one of the primary strategies in tumor therapy." (PMID 34215336, 2021). "A second IL-2 design fuses IL-2 to an antibody, such as epidermal growth factor receptor, which “actively” targets specific proteins on tumor cells." (PMID 33986267, 2021). "Here, the authors design a cytokine receptor-masked IL-2 mutein prodrug that is selectively activated by matrix metalloproteinases in the tumor microenvironment, promoting anti-tumor immune response while minimizing systemic toxicity." (PMID 33986267, 2021). "IL-2 stimulates the growth of thymocytes and, as a result, induces T-cell differentiation and prompts the immune system to attack tumor cells." (PMID 34307161, 2021). "Studies on osteosarcoma treated with an IL-2 secreting Salmonella have shown the tumor repression effect in mice model." (PMID 33717106, 2021). "The authors challenged the system with a variant of IL-2, a bispecific antibody that binds to carcinoembryonic antigen (CEA, an antigen overexpressed on different tumour cells) and to CD3 (T lymphocytes), and the combination of these." (PMID 34572836, 2021). "Use of cytokines like IL-2, IL-15, IL-12, IL-21 and IL-18 is considered a promising approach to induction of more efficient NK cell activation at tumor sites, while IL-15 and IL-21 can enhance NK cell cytotoxicity." (PMID 34177887, 2021). "These factors, along with IL-2, subsequently activate STAT3 signaling in tumor associated-TRegs to promote their expansion." (PMID 34483843, 2021). "Eighteen days after tumor inoculation, mice were sacrificed, and splenocytes were prepared and restimulated with neoepitope Ag and IL-2 to confirm the generation of cytotoxic effector cells." (PMID 34862254, 2021). "These tumor fragments were cultured for about 4 weeks in culture medium containing interleukin-2 (IL-2)." (PMID 34321276, 2021). "This drug-conjugated immunocytokine retained IL-2 signaling in T cells and tumor-homing capabilities, but it exhibited a significant increase in tumor control with no elevation of toxicity." (PMID 33803078, 2021). "IL-2 therapy has been used to increase the per capita growth rate of T cells in vivo and is the key driver of ex vivo expansion of tumor infiltrating lymphocytes (TIL) used for TIL-based immunotherapy in cancer." (PMID 34531851, 2021). "In an in vivo setting, the forced increased expression of IL2, by transfection, in tumor exosomes showed better immunogenicity against lymphoma cells compared with nontransfected tumor exosomes." (PMID 33679988, 2021).
tumor (continued). "Initially, these cells are isolated from homogenized tumors or sentinel lymph nodes and then cultured with IL-2 in the presence of tumor lysate as a source of tumor-antigens and peripheral blood mononuclear cells (PBMC) for efficient antigen presentation." (PMID 33670139, 2021). "For example, Cheng and colleagues developed IL-2-loaded PLGA NP entrapped in tumor cell lysate-pulsed BMDC-derived membranes (MiniDC)." (PMID 34359665, 2021). "TILs were grown from tumor fragments, expanded in vitro and reinfused to the patient preceded by a lymphodepleting chemotherapy regimen and followed by interleukin-2 infusion." (PMID 34210820, 2021). "A great amount of focus has been on improving survival, proliferation, and effector function of CD4+ and CD8+ T cells, but other immune cells such as NK cells also readily respond to IL-2 and are important for mediating cytotoxicity towards tumor cells." (PMID 34790830, 2021). "This was followed by studies documenting in vitro sensitization of immune lymphocytes by tumor cells, expansion of sensitized cells using IL-2 and the ability of the expanded lymphocytes to attack tumors." (PMID 33671123, 2021). "These include Bempegaldesleukin (BEMPEG/NKTR-214), a CD122-preferential IL-2 pathway agonist demonstrating promising anti-tumour efficacy in pre-clinical studies of advanced cancer in combination with ICB and local radiation therapy." (PMID 34960140, 2021). "Utilizing an IL-2 immunocytokine-targeting Tnc A1 augmented the control of tumor progression for both paclitaxel and doxorubicin in breast cancer-bearing mice without additional toxicity." (PMID 33803078, 2021). "CD39/CD73 produce extracellular adenosine which accumulates in the TME and inhibits anti-tumour T-cell responses by reducing antigen-induced proliferation and IL-2 and IFN-γ production." (PMID 34944851, 2021). "Although high-dose IL-2 has certain ability to activate the anti-tumor immune response, the consequent severe adverse effect and high levels of Tregs significantly limit its clinical benefit." (PMID 33746989, 2021). "As CD25 is also transiently expressed on a small population of activated Teff cells, IL-2 can stimulate the effector T cells through the IL-2 receptor complex to facilitate tumor suppression." (PMID 34824364, 2021). "Our results showed that MDSCs from the spleen of tumor bearing MUC1KO mice were more effective in inducing T cell suppression indicated by lower IL-2 and IFN-γ production by T cells." (PMID 34070449, 2021). "Here, we find that engaging NK cells and macrophages through an anti-tumor antibody and IL-2 (for NK cells) can therapeutically drive such chemokine and FLT3L production in the TME." (PMID 34818534, 2021). "Non-IL2 blocking BT942 also demonstrates significant stronger efficacy than the IL-2 blocking daclizumab in the MC38 syngeneic tumor model." (PMID 34824364, 2021). "JVZ-007 was constructed with the CD28 transmembrane, co-stimulatory domain and CD3ζ signaling domain, which responded to PSMA+ tumor cells, LNCaP and DU-145, by inducing IL2 and INF-γ secretion and increasing CD69 expression." (PMID 33567640, 2021). "Tumor samples were assessed at the mRNA level for the expression of hamster endogenous IL-2 production and transgene expression." (PMID 34084172, 2021). "IL-2 mutants display enhanced anti-tumor effects due to preferential activation of CD8 T cells and NK cells, and decreased expansion of Tregs." (PMID 34804041, 2021). "The mechanisms of this anti-inflammatory effect of CIMVs-IL2 requires more detailed examination, alongside the anti-tumor properties of CIMVs-IL2." (PMID 33579033, 2021). "Preclinical analysis demonstrated that pro-IL2 had comparable anti-tumor efficacy to sumIL2-Fc with a superior toxicity profile." (PMID 34790830, 2021). "When vaccinated with P2Et-pretreated 4T1 cells, the primary tumor growth was improved by yielding IL-2, TNFα, IL-4, IL-5, and IFNγ-producing CD4+ and CD8+ T lymphocytes." (PMID 34948368, 2021).
tumor (continued). "Meanwhile, IFN-γ, TNF-α, IL-2, and IL-1β play crucial parts in killing tumor cells according to previous researches." (PMID 34721026, 2021). "In contrast, cytokines involved in tumour suppression such as IL-1ra, IL-2, and IL-12 were also elevated." (PMID 34315989, 2021). "An initial study investigating targeted IL-2 to EDB showed sufficient trafficking to the tumor vessels after intravenous administration and a significant reduction in tumor growth compared to saline, unconjugated IL-2, and parental antibody groups." (PMID 33803078, 2021). "We discovered that CAR-T cells expanded with IL-15 had reduced dysfunction and enhanced persistence compared to those grown with IL-2 or a combination of IL-15 and IL-7, which resulted in longer and improved anti-tumor responses in a mouse model." (PMID 34298748, 2021). "As a consequence, exosomes isolated from breast tumor cells pretreated with curcumin showed a lowered capacity of inhibiting IL-2-stimulated NK cell tumor cytotoxicity." (PMID 33572626, 2021). "As early as 1.5 hours after the treatment, intratumoral CD8 T and NK cells showed augmented IFN-γ and IL-2 expression, indicating their activation and tumor cell killing." (PMID 34725216, 2021). "It demonstrated that granulocyte-macrophage colony stimulating factor (GM-CSF) provided the most durable and specific anti-tumour immunity compared to other immunomodulatory cytokines (e.g., IL-2, IL-4, IL-6 and IFN-γ)." (PMID 34944851, 2021). "The CD40 pathway has been demonstrated to be a key regulator of cytokine production, including IL-2, and anti-tumor immune response." (PMID 34830445, 2021). "Lastly, the cytokine interleukin 2 (IL-2) has been found to convert TAMs from a pro-tumorigenic mode to a tumor inhibiting state and attempts are underway to deliver them to the TME using nanoparticles." (PMID 33668200, 2021). "In a MC38-OVA tumor model, GR-deficient CD8 T cells expressed higher IL-2, TNF-α, and IFN-γ; blocked tumor-growth and were less exhausted." (PMID 34691020, 2021). "In mice, these second generation ΔCD28/CD3ζ and third generation ΔCD28-4-1BBζ CAR T cells show reduced IL-2 production and improved tumor control in the presence of Tregs." (PMID 34012443, 2021). "This PEGylated IL-2 exhibited greater tumor retention and circulation half-life, increased infiltrating CD8+ T cells, and had superior tumor growth inhibition compared to unconjugated IL-2 in multiple murine models." (PMID 33803078, 2021). "Exogenous IL-2 is supplied during these cultures to reinvigorate exhausted T cells that were extracted from the tumor tissue." (PMID 34571883, 2021). "Tumor fragments of three primary tumors were cultured in IL-2 (6000 IU/ml) + anti-4-1BB antibody (10 ug/ml) and these fragments yielded higher numbers of expanded TIL compared to fragments of the same tumors cultured only in IL-2 (6000 IU/ml) (p=0.006)." (PMID 33717150, 2021). "Briefly, adoptive TILs therapy is based on isolation of TILs from tumor environment, ex vivo activation and expansion with the help of high-doses of interleukin-2 (IL-2), and finally infusion back into the patient." (PMID 34885122, 2021). "Activation of natural killer (NK) cell function is regulated by cytokines, such as IL-2, and secreted factors upregulated in the tumor microenvironment, such as platelet-derived growth factor D (PDGF-DD)." (PMID 34858395, 2021). "Anti-IL-23A monoclonal antibody treatment synergistically suppressed tumor growth and metastases in combination with either targeted therapies or IL-2." (PMID 34093846, 2021). "Specific delivery of IL-2 with the NKG2D-Fc system led to the expansion of tumour antigen-specific CD8+ T cells at the tumour loci and an improved therapeutic anti-tumour effect generated by the therapeutic DNA HPV vaccine." (PMID 33800608, 2021). "As such, these immunocytokines increase the therapeutic window compared to unconjugated IL-2 and seem dependent on immune effector cells to illicit an anti-tumor response." (PMID 33803078, 2021).
tumor (continued). "We evaluated their anti-tumor efficacy when used as single agents or in combinatorial treatments with anti-CTLA-4 mAbs in in vitro co-cultures of hPBMCs with tumor cells, by measuring tumor cell lysis and IL-2 and IFNγ cytokines secretion by lymphocytes." (PMID 35008285, 2021). "Group C animals receiving additional ASA and low-dose IL-2 demonstrated a significantly lower tumor burden that decreased over time compared to Groups A (P = 0.008) and B (P = 0.004)." (PMID 33723260, 2021). "Next, IL-2-activated NK cells were added to pre-treated tumor spheroids, and the spheroids’ growth was monitored." (PMID 34683961, 2021). "In other cancers, 29% of kidney cancer patients achieved objective tumor responses with the treatment of autologous TILs and continuous IL-2 infusion." (PMID 34553029, 2021). "In contrast, tumors such as HNSCC and melanoma have been characterized as the most Treg infiltrated tumor types, making the use of IL-2 in combination with cetuximab less attractive." (PMID 34557197, 2021). "IL2RB activation via endogenous IL2 or biased therapeutic stimulation results in the expansion of anti-tumor immune cells, in particular CD8+, CD4+ and NK cells." (PMID 33928242, 2021). "Low pH condition, caused by the accumulation of excessive lactic acid, inhibits the secretion of IL-2, tumor necrosis factors, and IFN-γ from T lymphocytes." (PMID 34484235, 2021). "The use of EVs can increase the efficacy of IL2-based anti-tumor therapy whilst reducing systemic toxicity." (PMID 33579033, 2021). "Protein kinase C gamma (PRKCG), as an isoenzyme of protein kinase Cs (PKCs), mediates IL-2 expression and tumor immune response." (PMID 35155566, 2021). "TILs therapy requires the isolation of tumor-infiltrating lymphocytes from the tumors, expansion by IL-2 treatment, and reinfused into the patients with additional IL-2 treatment." (PMID 34178657, 2021). "We have previously demonstrated that IFN-γ secreted by IL-2+anti-CD16 mAb-treated NK cells promotes tumor differentiation." (PMID 33440654, 2021). "Proinflammatory cytokines such as IFNα, IL-2, IL-10, IL-12, IL-15 and GM-CSF have been tested for anti-tumor effects with varying success." (PMID 33968029, 2021). "Each patient received a combination of Melan-A and MELOE-1 polyclonal specific T-cells, whose specificity and anti-tumor reactivity were checked prior to injection, with subcutaneous IL-2." (PMID 34120214, 2021). "Similar to IL-2, stimulation with IL-15 is able to enhance the antitumor effects of NK cells against various tumor types and significantly increases cytokine and chemokine secretions." (PMID 34557197, 2021). "At first, aiming to incorporate cytokines’ function into the models, Kirschner and Panetta built a three-ODE system addressing the potential of IL-2 and its effects on tumor relapse." (PMID 34371708, 2021). "T-cell stimulatory common γ chain cytokines IL-7, IL-15, or IL-21 are capable of supporting the generation of memory cells with improved mitochondrial fitness and less overt T-cell differentiation compared to the use of IL-2, improving anti-tumour immunity." (PMID 34960140, 2021). "In a human multicenter phase I study, NKTR-214, a novel IL-2 pathway agonist, showed clinical activity including tumor shrinkage and durable disease stabilization in heavily pretreated patients." (PMID 35095898, 2021). "Further, the acidic TME impairs the secretion of proinflammatory cytokines by T-cells (e.g., IL-2, TNFs and IFN-γ) and upregulates CTLA-4 expression, rendering tumour infiltrating T-cells more susceptible to negative regulatory signals." (PMID 33923305, 2021). "From this point, DN Teff cells become reluctant to continuous TCR engagement (‘desensitized’ to the cognate tumor antigens) but are still responsive to IL-2 available in the TME, promoting re-expression of CD45RA for the differentiation of DN Temra cells." (PMID 34593620, 2021).